CD80 (CD80 molecule)
Diseases named in the same sentence as CD80 in open-access papers (continued):
Sharing a sentence is not in itself a finding about the gene and the disease.
psoriasis (15 papers, 2010 to 2025). An autoimmune condition characterized by red, well-delineated plaques with silvery scales that are usually on the extensor surfaces and scalp. "Last, we outline how preventing PD-L1:CD80 interactions or mutating the PD-L1 cytoplasmic domain in a model of psoriasis limits DC migration, interleukin-17 (IL-17) production by CD4+ T cells, and epidermal thickening associated with disease." (PMID 39879305, 2025). "The number of dendritic cells, marked by CD86 and CD80 antibodies and playing a critical role in the local inflammatory response in psoriasis, and CD4+ cells in the dermis was also decreased after TBTDC NP-PDT." (PMID 39109246, 2024). "Although cytokines such as IL-17, IL-23, and IL-1β are mainly involved in the exacerbation of psoriasis, DC–T cell crosstalk through CD80/CD86 also affects psoriasis." (PMID 34421919, 2021). "Analysis of cell surface markers expression on B cells (i.e., CD40, CD44, CD80, CD86,CD11b, and HLA-DR) is the key to understand their pathogenic role in psoriasis." (PMID 27532281, 2016). "We also found an elevatedratio of CD19+CD80+ B cells in the PBMCs from all subtypes of psoriasis in this study(except for psoriasis vulgaris at the stationary stage)." (PMID 27532281, 2016). "It was concluded that CD28/CD80 is crucial in promoting T cell inflammation in psoriasis and the effect of blocking CD28/CD80 signalling by CTLA-4 analogues or by anti-CD28 blocking antibodies is effective against PsA." (PMID 24676037, 2014). "Consistently, the role of CD28/CD80 in experimental models of psoriasis and in humans has been recently reviewed." (PMID 24676037, 2014). "Upregulation of CD80/CD86 in psoriatic lesions suggests a critical role for the CD28/B7 co-stimulatory system in the pathogenesis of psoriasis." (PMID 20606886, 2010). "Thus, inhibition of the CD28 and CD80/CD86 interaction is expected to restrict the inflammatory processes of psoriasis." (PMID 20606886, 2010). "Blocking PD-L1:CD80 interactions prevents DC migration and limits TH17 responses during imiquimod induced psoriasis." (PMID 39879305, 2025). "In this study, we expand on these findings by demonstrating that like PD-L1, CD80 was required for efficient DC migration to the dLN and that blocking PD-L1:CD80 cis interactions could lessen the severity of IMQ-induced psoriasis driven by dermal DCs." (PMID 39879305, 2025). "In the last 10–15 years, the introduction of biological therapies, such as TNF-α, IL-12/23, and IL-17 inhibitors in psoriasis and IL-6, CD20, TNF-α, and CD80/86 inhibitors in RA, is expected to influence the rate of atherothrombotic complications in patients with psoriasis and RA." (PMID 38927529, 2024). "Therefore, our results confirm that CD40, CD44, CD80, and CD86 are likelyimportant in the pathogenesis of psoriasis, especially at the active stage." (PMID 27532281, 2016). "The proportion of CD19+CD80+ B cells in PBMCs from patients withpsoriasis vulgaris at the active stage (P<0.001), but not the stationary stage,and all other different psoriasis subtypes (all P<0.01) was upregulated comparedwith HCs." (PMID 27532281, 2016).
minimal change disease (14 papers, 2013 to 2024). "CD80, which regulates T cell activation, may provide a differential diagnostic marker between minimal change disease (MCD) and other renal diseases, including focal segmental glomerular sclerosis (FSGS)." (PMID 30470792, 2018). "CD80 is also expressed on antigen-presenting cells (APCs) of patients with Minimal Change Nephropathy." (PMID 39575257, 2024). "Data from a second study by the same group showed that urinary CD80 was increased in patients with minimal change disease in relapse compared to patients with minimal change disease in remission or those with FSGS." (PMID 24327929, 2013). "It is possible that IL-13, a known stimulator of the IgE response, may mediate proteinuria in patients with minimal change disease by directly inducing CD80 expression in the podocyte." (PMID 28035995, 2016). "Urinary CD80, however, appears to be elevated in minimal change disease (especially minimal change disease in relapse) and not in FSGS." (PMID 27314022, 2016).
type 1 diabetes (14 papers, 2009 to 2023). "We generated a novel HLA-transgenic mouse model that expresses high-risk genes for type 1 diabetes (DRB1*03:01-DQA1*05:01-DQB1*02:01) as well as human CD80 under the rat insulin promoter and human CD4, on a C57BL/6 background." (PMID 31612266, 2019). "Guo developed an algorithm for identifying steering nodes to a gene regulatory network related to type 1 diabetes and they found that FASLG and CD80 are steering nodes for controlling the target nodes related to type 1 diabetes and supported by wet experiments." (PMID 33968733, 2021). "One of the notable characteristics of the DC generated from monocytic progenitors in the presence of the mixture of antisense DNA targeting the primary transcripts of CD40, CD80, and CD86 used in the phase I type 1 diabetes safety trial is their ability to produce retinoic acid (RA)." (PMID 29774025, 2018).
colorectal cancer (13 papers, 2004 to 2025). A primary or metastatic malignant neoplasm that affects the colon or rectum. "In this study, we aimed to establish recombinant Lactococcus lactis carrying the human soluble CD80 (hsCD80) gene for colorectal cancer therapy." (PMID 37476068, 2023). "Considering the high cost and inconvenience of recombinant CD80 injection, we constructed recombinant L. lactis bearing the hsCD80 gene for colorectal cancer therapy." (PMID 37476068, 2023). "Compared with MMR proficient colorectal cancers, MMR-deficient tumors presented a higher T helper 1 and cytotoxic T cell infiltration, together with a higher rate of CD80 expression." (PMID 26496037, 2015). "Indeed, our observation of a higher expression rate of CD80 in MMR-D CRC is consistent with a microarray analysis comparing the gene expression profiles of MSI-H colorectal cancers to MSS counterparts that demonstrated increased signal intensity of CD80 in the former group." (PMID 26496037, 2015). "Here, we profiled macrophages in a series of 150 colorectal cancer (CRC) cases by immunohistochemistry, using CD68 as a macrophage lineage marker, CD80 as a marker of pro-inflammatory macrophages, and CD163 as a marker of anti-inflammatory macrophages." (PMID 31481956, 2019). "Transcripts specific to co-stimulatory molecules (CD80 and CD86), HSP60, MHC peptides, pro-inflammatory cytokine receptors, Perforin 1 and Caspase 9 were amongst those that were up-regulated in MSI-H colorectal cancers." (PMID 15298707, 2004). "In addition, the expression levels of CD80 were increased in RAW264.7 macrophages by the exosomes, and CD80 has been shown to have a role in the immunosurveillance agent colorectal cancer in the early stages of tumorigenesis." (PMID 40001983, 2025). "Based on these data and the correlations with cytokine levels, it can be concluded that CD25, CD80, CD86, CD274 and CD279 glycoproteins combined with specific plasma levels of IL-1β, IL-2, IL-15 and TGFβ could represent potential biomarkers for colorectal cancer." (PMID 39456247, 2024).
Nephropathy (13 papers, 2014 to 2025). A nonspecific term referring to disease or damage of the kidneys. "Our group has also recently discovered that the xenograft nephropathy, the nephrotic syndrome associated following xenotransplantation, is also associated with the induction of CD80 expression in podocytes." (PMID 29687010, 2018). "The development of xenograft nephropathy following XKTx appears to be closely associated with upregulation of CD80 and loss of SMPDL-3b in porcine podocytes." (PMID 29687010, 2018). "In this study, we evaluated the concentration of urinary CD80 of 65 samples from 55 patients with various renal diseases, including inherited diseases, to determine the utility of urinary CD80 as a diagnostic biomarker." (PMID 30470792, 2018). "The CTLA-4 mimicking therapeutic agents, which binds CD80, have been tested in CD80-positive proteinuric kidney disease." (PMID 32509873, 2020). "Abatacept (cytotoxic T-lymphocyte–associated antigen 4–immunoglobulin fusion protein [CTLA-4–Ig]), a costimulatory inhibitor that targets CD80, has been used in CD80-accociated nephropathy." (PMID 30083478, 2018). "The present study was performed to determine the utility of urinary CD80 measurement for the differential diagnosis of patients with various renal diseases." (PMID 30470792, 2018). "In an animal model of glomerulonephritis, it was evident that CD80 plays a detrimental role in kidney disease by promoting CD4+ survival and proliferation." (PMID 26063968, 2015). "However, studies have shown that CD80 is elevated to varying degrees in patients with active kidney disease." (PMID 40236664, 2025). "These might include TGF-b1, CD80, podocalyxin, podocin, nephrin or uromodulin as nephropathy related biomarkers, and S1P or IL-18 as biomarkers more related to cardiomyopathy." (PMID 33924567, 2021). "The level of CD80 was elevated in all patients with active kidney disease." (PMID 30470792, 2018). "To investigate whether elevated urinary CD80 in MCD in relapse has specificity for other renal diseases, we compared urinary CD80 values between MCD in relapse and all renal diseases other than MCD." (PMID 30470792, 2018). "Increased urinary CD80 excretion was present in all patients with active kidney disease." (PMID 30470792, 2018). "All these reports showed elevation of urinary CD80 only in patients with MCD in relapse, with levels remaining normal in controls, patients with MCD in remission, FSGS or other renal diseases." (PMID 30470792, 2018). "Therefore, we judged that urinary CD80 might not be a useful diagnostic marker for renal diseases, and we decided not to collect more samples." (PMID 30470792, 2018). "From these results, it was hypothesized that the level of urinary CD80 was useful as a biomarker to distinguish between MCD patients in relapse and other renal diseases, including FSGS13." (PMID 30470792, 2018). "In conclusion, our results showed that urinary CD80 was not a reliable differential diagnostic marker between MCD in relapse and FSGS or other kidney diseases, including inherited kidney diseases, in contrast to previous reports." (PMID 30470792, 2018). "This might mean that excretion of urinary CD80 may increase in patients with active renal disease, rather than upon activation of T cells." (PMID 30470792, 2018). "We suggest that measuring urinary CD80 levels is not a reliable marker for the differential diagnosis of MCD in relapse and other kidney diseases." (PMID 30470792, 2018).
nephrotic syndrome (13 papers, 2014 to 2023). A collection of symptoms that include severe edema, proteinuria, and hypoalbuminemia; it is indicative of renal dysfunction. "Additional molecules including hemopexin, angiopoietin-like-4 and CD80 are associated with nephrotic syndrome and have also been shown to cause proteinuria in experimental animals but do not appear to be relevant to FSGS." (PMID 27104120, 2016). "Moreover, MCD, the most common cause of proteinuria and nephrotic syndrome in children, has been associated with high levels of CD80 in the urine as well as with CD80 expression in glomerular podocytes in renal biopsies." (PMID 29687010, 2018). "In a pediatric study, 64 patients with nephrotic syndrome were evaluated for their urinary CD80 levels." (PMID 37298105, 2023). "It seems feasible to employ urinary CD80 as a marker of nephrotic syndrome in adults, given that it appears to correlate with serum albumin and proteinuria, albeit lacking specificity for MCD." (PMID 36673014, 2023). "Recent studies on CD80 as a urinary biomarker have provided new evidence for its potential use as biomarker in the context of nephrotic syndrome." (PMID 37298105, 2023). "They concluded CD80 to be a discriminator of MCD from other forms of nephrotic syndrome, especially secondary FSGS." (PMID 37298105, 2023). "We have also found elevated levels of urinary CD80 excretion in a patient presenting with nephrotic syndrome following bone marrow transplant, as well as in a few patients with posttransplant FSGS (unpublished)." (PMID 29687010, 2018). "Elevation of urinary CD80 was observed, even in patients with inherited nephrotic syndrome unrelated to T cell activation." (PMID 30470792, 2018). "Recently, urinary levels of CD80 were reported to be extremely high in a patient who developed minimal change-like nephrotic syndrome following allogeneic stem cell transplantation." (PMID 29687010, 2018). "Our previous study proved that the change of urinary CD80 concentration could predict the recurrence of steroid-sensitive nephrotic syndrome." (PMID 32509873, 2020). "The present study aimed to evaluate the expression of CD80 and CD18 in subpopulations of peripheral blood leukocytes and oxidative kidney damage in rats with nephrotic syndrome (NS) induced by doxorubicin (Dox) in comparison to control animals at different time points." (PMID 26063968, 2015). "Moreover, podocytes express B7-1 (also known as CD80), a co-stimulatory molecule for T cells which is inducible under conditions of stress and was first reported in the context of the nephrotic syndrome." (PMID 37564655, 2023).
acute myeloid leukemia (11 papers, 2015 to 2025). Acute myeloid leukemia (AML) is a group of neoplasms arising from precursor cells committed to the myeloid cell-line differentiation. "For example, co-expression of IL-15/IL-15Rα and CD80 in syngeneic acute myeloid leukemia (AML) vaccines generated potent, durable anti-leukemic immunity, yielding 50% overall survival in murine models." (PMID 41196843, 2025). "In a model of acute myeloid leukemia, the expression by cancer cells of the immune checkpoints CD274 (best known as PD-L1) and CD80 (also known as B7.1) prevented T cell activity and preserved cancer dormancy." (PMID 33193295, 2020). "Similarly, Acute myeloid leukemia (AML) blasts modified with IL-2/CD80 as a vaccine in vitro can induce peripheral blood mononuclear cells from AML patients to secrete higher levels of IFN-γand show stronger lytic activity against autologous, unmodified blasts." (PMID 39575257, 2024). "Particularly, DNMT and HDAC inhibitors may result to an upregulation of TAAs and of co-stimulatory molecules such as CD40, CD80, CD86 and MHC classes I and II, on tumor cells, in particular in Acute Myeloid Leukemia (AML) cell lines." (PMID 39086678, 2023). "We evaluated the response of J76 PRAME TPR expressing CD2::CD28 receptors to primary acute myeloid leukemia (AML) cells that express no CD28 ligands CD80 and CD86." (PMID 29707134, 2018). "We hypothesized that CD80 would be expressed on tumor cells in dogs from acute myeloid leukemia (AML) but not dogs with lymphoid neoplasms." (PMID 39224452, 2024).
gastric cancer (11 papers, 2012 to 2025). A primary or metastatic malignant neoplasm involving the stomach. "Several identified hub genes, including CXCL1, CCL20, IL12B, STAT4, and CD80, are involved in chemokine signaling, immune modulation, and inflammation, which can promote H. pylori–mediated gastric cancer." (PMID 40445003, 2025). "As a result, it was seen that CD80 is downregulated in gastric cancer tissues in 15 out of 20 patients compared to normal gastric tissue." (PMID 37765273, 2023). "Decreased expression of CD80 was found in gastric cancer, which is consistent with our experimental results, and gene therapy with CD80 inhibits metastasis 24,27,29." (PMID 32025206, 2020). "PPI network analysis highlighted eight key hub genes (CD80, CCR9, CXCR3, CXCR5, CXCR6, CCR3, CCL20, and CXCL1), revealing their pivotal roles in gastric cancer and H. pylori infection." (PMID 40445003, 2025). "The selection of target proteins was guided by overexpression data obtained from gastric cancer cell lines, specifically focusing on genes such as AJUBA, CD80 and NOLC1." (PMID 37765273, 2023). "For example, CD80 and CD86 are markers of M1 macrophages, which can inhibit tumor growth of gastric cancer." (PMID 37274740, 2023). "Another research showed that the SNP rs1599795 in CD80 3′‐UTR, through disrupting the regulatory role of miR‐212‐3p in CD80 expression, contributed to tumorigenesis of gastric cancer." (PMID 32767729, 2020).
osteosarcoma (11 papers, 2015 to 2025). A usually aggressive malignant bone-forming mesenchymal neoplasm, predominantly affecting adolescents and young adults. "This study illustrated that increased CD80+CD62L+ myeloid dendritic cells appeared to be linked with osteosarcoma risk." (PMID 39081321, 2024). "The causality between CD80 on CD62L+ myeloid dendritic cell and osteosarcoma risk remained consistent across other methods, such as weighted median and weighted mode." (PMID 39081321, 2024). "An experimental study found that infection upregulates the inflammatory immune response mediated by canine macrophages, counteracting osteosarcoma-induced immune suppression through increasing CD80 expression." (PMID 39081321, 2024). "IONPs, functioned with n-hydroxysuccinimide, were conjugated with vascular endothelial growth factor (VEGF) antibody and ligand cluster of differentiation 80 (CD80) (IONPs@CD80 + VEGF) to treat human osteosarcoma." (PMID 38191388, 2024). "Though the exact function of expression of CTLA-4 on tumor cells is unknown, incubating the cells with CTLA-4 ligands CD80 or CD86 induced apoptosis in human osteosarcoma cell line HOS cells through caspase-3 and caspase-8 activation." (PMID 33823818, 2021). "The expression of M1 phenotype markers CD80 and FCGR1A were also downregulated in metastatic osteosarcoma, suggesting that the decreased macrophage M1 might associate with the osteosarcoma metastasis." (PMID 34335756, 2021). "Specifically, CD80 expression on CD62L+ myeloid dendritic cells (OR: 3.41 [95% CI: 1.40 to 8.31], p = 0.007) and the absolute count of CD28−CD4−CD8− T cells (OR: 4.49 [95% CI: 1.29 to 15.62], p = 0.018) were found be positively associated with osteosarcoma in the IVW analysis." (PMID 39081321, 2024). "To determine if T cell responses to osteosarcoma metastatses in α-PD-L1 mAb treated mice may have become tolerized through engagement of other inhibitory ligands, we evaluated expression of PD-L1, CD80, and CD86 on metastatic osteosarcoma cells, in both mock treated and α-PD-L1 mAb treated mice." (PMID 25992292, 2015). "In the TARGET osteosarcoma cohort, IL18 expression was positively correlated with M1 marker CD80 and CD86 and M1 abundance in tumor-infiltrating immune cells." (PMID 36274066, 2022). "In order to clarify the role of macrophages in osteosarcoma, future studies should correlate the presence of CD68+/CD80+ M1 and CD68+/CD163+ M2 macrophages to osteosarcoma survival." (PMID 27456063, 2016). "Our findings found that CD80 on CD62L+ myeloid dendritic cells and CD28−CD4−CD8− T-cell absolute count are positively associated with OS, and CD20 on CD24+CD27+ B cells and CD20 on IgD+ CD38 B cells have a negative effect on osteosarcoma." (PMID 39081321, 2024). "Moreover, CD80 and CD86 expression on metastatic osteosarcoma was significantly increased after α-PD-L1 mAb treatment suggesting that tumor cells may be directly or indirectly using this pathway to suppress CTL-mediated killing." (PMID 25992292, 2015).